REN (renin)
Diseases named in the same sentence as REN in open-access papers (continued):
Sharing a sentence is not in itself a finding about the gene and the disease.
Hypertension (continued). "By clipping the renal artery, the renin–angiotensin system is activated, inducing the upregulation of renin release in the first weeks after surgery and leading to increases in angiotensin II and hypertension." (PMID 35890152, 2022). "Angiotensin-converting enzyme I (ACE I) is a zinc-containing metallopeptidase involved in the renin-angiotensin system (RAAS) that helps in the regulation of hypertension and maintains fluid balance otherwise, which results in cardiovascular diseases (CVDs)." (PMID 36505231, 2022). "TGF-β1 also stimulates the expression of TWIST1, and C3 stimulates the expression of renin to induce hypertension." (PMID 36018840, 2022). "Hydroxychloroquine was widely accepted as a concomitant measure followed by renin-angiotensin system inhibitors in cases of arterial hypertension and/or proteinuria." (PMID 35529329, 2022). "The role of the renin-angiotensin system (RAS) in hypertension and emotional disorders is well established." (PMID 36761172, 2022). "At present, western medicine mainly focuses on controlling blood glucose, hypertension and inhibiting the renin-angiotensin system, which can only partially ameliorate but not prevent the development of renal failure." (PMID 35618411, 2022). "When PA is suspected in a patient with hypertension, a plasma aldosterone to renin ratio (ARR) will be obtained initially." (PMID 35614110, 2022). "The laboratory test currently used that helps to initially differentiate the source of hypertension and thus supports treatment is the determination of plasma renin activity (PRA)." (PMID 36611307, 2022). "Olfr78 role in hypertension was characterized primarily in the renal afferent arterioles, where it was related to the release of renin after stimulus with propionate." (PMID 36246106, 2022). "Apelin/APJ system induces hypertension via affecting sympathetic nervous system, renin–angiotensin–aldosterone system, endothelial injury, excessive endothelin, sodium retention and vascular remodeling." (PMID 35831335, 2022). "As another example, hypertension and cardiovascular disease often involve overactive signaling in the angiotensin-renin system (RAS) and dysfunction in the adrenal system (epinephrine and norepinephrine)." (PMID 34418449, 2022). "PA is characterized by arterial hypertension, spontaneous hypokalemia, hyperkalemia, hyperaldosteronism, and reduced plasma renin activity." (PMID 35795736, 2022). "The renin angiotensin aldosteron system is important for hydromineral balance and it has a well-established role in the genesis of hypertension." (PMID 35722103, 2022). "Hypertension, increased adrenal aldosterone secretion and suppressed renin are the three hallmarks of primary aldosteronism." (PMID 35204632, 2022). "Agents acting on the renin-angiotensin system have several benefits like reducing blood pressure and proteinuria, being drug of choice for hypertension in DM, and decreasing cardiovascular mortality and morbidity." (PMID 36203125, 2022). "RESV modulates the renin-angiotensin system and enhances the production of nitrogen monoxide (NO), thus proved to be effective in the pathomechanism of hypertension, atherosclerosis, or ischemic heart disease." (PMID 35761875, 2022). "For example, renal artery stenosis and renal parenchymal lesions can release large amounts of renin from juxtaglomerular cells, resulting in increased Ang-2 activity and systemic arteriole wall contraction and subsequently resulting in hypertension." (PMID 35993052, 2022). "These laboratory and animal studies demonstrated that VDR knocks out mice who developed hypertension and found that vitamin D helps regulate the renin-angiotensin-aldosterone system by suppressing renin gene expression." (PMID 36382764, 2022). "An earlier study demonstrated that several factors in the body of with uremic patients, such as sodium and water retention and renin–angiotensin–aldosterone system activation, participate in the development of hypertension." (PMID 35964127, 2022).
Hypertension (continued). "A direct effect of SCFAs on renin release and vasomotor function leading to blood pressure reduction was recently suggested in experimental hypertension, and propionate treatment shows a blood pressure-lowering effect in the hypertensive mice." (PMID 35899110, 2022). "Even in patients presenting late in life and in the presence of CKD, PHA II should be suspected if renin levels are low and hyperkalemic acidosis and hypertension are inadequate for CKD stage, particularly in the presence of a suspicious family history." (PMID 35093948, 2022). "PA consists in a heterogeneous group of familial and sporadic disorders characterized by hypertension secondary to overproduction of aldosterone, low plasma renin activity, and low potassium levels." (PMID 36313775, 2022). "It has been shown that sex hormones affect systems that are considered to play an important part in the development of hypertension, such as renin angiotensin aldosterone system, endothelin, nitric oxide (NO) system and immune system." (PMID 35722103, 2022). "The activation of the renin-angiotensin-aldosterone system (RAAS) is the main mechanism by which obesity induces the development of high blood pressure." (PMID 36145220, 2022). "It is known that some populations abuse salt and other populations are predisposed to hypervolemia such as African American patients in whom low‐renin essential hypertension is easily found." (PMID 36210543, 2022). "Recent study reported that renin-angiotensin-aldosterone system-related miR-483-3p is reduced in patients with essential hypertension." (PMID 35222797, 2022). "In patients with diabetes mellitus, high blood pressure, or cardiovascular disease, there are changes in the renin–angiotensin system, a decreased number of angiotensin-converting enzyme 2 receptors with consequences on the gut microbiota (dysbiosis)." (PMID 35801777, 2022). "High blood pressure (hypertension) and high blood cholesterol can contribute to the exacerbation of atherosclerosis through several mechanisms, such as the renin–angiotensin–aldosterone system (RAAS), impaired endothelial function, and oxidative stress." (PMID 35454125, 2022). "It has been proved that the changes in cardiac output and renin–angiotensin–aldosterone system activation consequence of excess weight can lead to high blood pressure." (PMID 35883048, 2022). "The main symptoms are high blood pressure and hypokalemia, the diagnosis seems to be based on the determination of aldosterone and plasma renin activity, also the treatment includes majorly adrenalectomy." (PMID 36699970, 2022). "The vascular dysfunction of the renal artery can cause decreased renal perfusion in both sexes in the long term, affecting the function of the renin-angiotensin-aldosterone system that can contribute to further vascular dysfunction and hypertension." (PMID 33671779, 2021). "Renal arterial dysfunction plays an important role in the development of hypertension through its function in the regulation of renal blood flow, influencing renin-angiotensin-aldosterone axis." (PMID 33671779, 2021). "Urinary angiotensinogen (AGT) is an index of intrarenal renin-angiotensin system (RAS) status with hypertension and progression to CKD being prominent features of (untreated) ADPKD." (PMID 34206927, 2021). "All of them had previous comorbidities (hypertension and obesity were the most common), and 14 of them took renin–angiotensin–aldosterone-system (RAAS)-modulating drugs." (PMID 33026628, 2021). "Renin-angiotensin system inhibitors (RASIs), β-blockers (BBs), calcium channel blockers (CCBs), and diuretics are widely used to treat patients with hypertension." (PMID 34054514, 2021). "Mervaala and colleagues documented that rodents with over-expressed human renin and angiotensinogen genes have raised XO activity with endothelial dysfunction and hypertension." (PMID 33639960, 2021).
Hypertension (continued). "Meanwhile, CRP has also been reported to have proatherogenic properties by upregulating the expression of angiotensin type I receptors, thereby affecting the renin-angiotensin system and participating in the pathogenesis of hypertension." (PMID 34925916, 2021). "Another etiological factor used for inducing hypertension is the Renin–Angiotensin System (RAS), in which Angiotensin-II (AngII) plays a pivotal role." (PMID 34827169, 2021). "The main factors and pathogenesis of hypertension are generally believed to be due to the fluid retention and renin-angiotensin-aldosterone system (RAAS) excessive activation." (PMID 33824765, 2021). "We then investigated the effects of LIT01-196, on BP in conscious hypertensive DOCA-salt rats, a salt- and volume-dependent model of hypertension, with low plasma renin levels, resistant to treatment with systemic RAS blockers." (PMID 34393794, 2021). "The foremost mechanism is an up-regulation of the renin-angiotensin system, which contribute to begin hypertension, heart failure and atherosclerosis." (PMID 34746061, 2021). "The most significant finding of this study is that the tetracycline antibiotic DOX treatment significantly contributes to the improvement of the vascular dysfunction and to a decrease in blood pressure in a low renin model of hypertension." (PMID 34578849, 2021). "Yet, when crossing female human AGT transgenic mice with male human renin transgenic mice, the pregnant mice did develop a pre-eclamptic phenotype, characterized by hypertension, elevated sFlt-1 levels and proteinuria." (PMID 34299027, 2021). "Similar to previous findings, some conventional factors, such as age, male gender, LVEF, hypertension, and oral renin-angiotensin system inhibitor and NSAID before surgery were predictors of AKI." (PMID 34372744, 2021). "Ang II type 1 receptor antagonists, as well as angiotensin-converting enzyme (ACE) and renin inhibitors, are widely used for treatment of hypertension." (PMID 33688433, 2021). "On the other hand, three targets in the renin-angiotensin system that have been extensively studied in the preclinical and clinical studies for the treatment of hypertension with vaccines include: renin, angiotensin I, and angiotensin II and its receptors." (PMID 34452161, 2021). "Potential mechanisms linking obesity to hypertension are many and growing evidence suggests the implication of the renin-angiotensin-aldosterone system (RAAS) in the pathogenesis." (PMID 34675881, 2021). "Hyperuricemia stimulates the renin-angiotensin system, and block the endothelial nitric oxide production, which contributes to renal vasoconstriction and hypertension." (PMID 33852602, 2021). "We previously observed that the 2Kidney-1Clip hypertension model elicits physical exercise and gastrointestinal dysmotility, which is prevented by renin-angiotensin system blockers." (PMID 34777003, 2021). "Obesity is known to induce hypertension through the mechanisms in stimulating the renin-angiotensin system and in increasing inflammatory response and oxidative stress via NADPH oxidase activation." (PMID 34959918, 2021). "Salt-sensitive hypertension is common in older adults; in addition, long-term drinking can accelerate the development of hypertension by damaging the renin-angiotensin system and impairing endothelial function, resulting in decreased salt sensitivity." (PMID 33622268, 2021). "Briefly, VDR deletion results in elevated production of renin and angiotensin II, leading to hypertension and cardiac hypertrophy." (PMID 33809311, 2021). "The clinical presentation of PsA is similar to that of primary aldosteronism and is characterized by peripheral edema, hypertension, laboratory hypokalemia, and lower plasma renin activity, due to the excessive action of mineralocorticoid receptors." (PMID 34604277, 2021).
Hypertension (continued). "Different oxidant status in the left and right kidney can be explained by the left kidney being ischemic and the right kidney having normal blood flow and being indirectly influenced by systemic hypertension and renin production by the left kidney." (PMID 34730891, 2021). "At present, there is a great controversy about the relationship between hypertension, use of renin–angiotensin–aldosterone system (RAAS) inhibitor drugs and COVID-19." (PMID 33789752, 2021). "All these findings showed that DOX produces beneficial effects on renin-angiotensin-dependent rodent models, implicating intimate involvement of gut microbiota in hypertension." (PMID 34578849, 2021). "The activation of the renin-angiotensin-aldosterone system is a permanent feature, common to all cardiovascular diseases, from arterial hypertension to chronic heart failure, and as such adds to the relevance of the model." (PMID 33467058, 2021). "As a result of increased renin level, angiotensin II increased and lead to the development of hypertension and cardiac hypertrophy in vitamin D receptor null mice." (PMID 34946242, 2021). "In our analyses, the renin-angiotensin system, metabolism of angiotensinogen to angiotensin, and peptide hormone metabolism pathways were found to be shared by both hypertension and COVID-19." (PMID 34067609, 2021). "Increased expression of βTGF, and activation of the renin-angiotensin system lead to hypertension, renal injury and finally poor prognosis in the IgAN patients." (PMID 35223400, 2021). "At baseline, when the two patients were free from specific therapy, with a florid disease characterized by low-renin, low-aldosterone hypokalemic hypertension, we observed a high exosomal HSD11B2 mRNA expression." (PMID 34497581, 2021). "Risks of mortality among Chinese herbal medicine users with chronic heart failure, hypertension, and ischemic heart disease under renin-angiotensin-aldosterone system inhibition therapy." (PMID 33973855, 2021). "Conventional hypertension therapies focus on strategies for attenuating the activity of the renin-angiotensin system or by decreasing sympathetic nerve activity, because adrenergic neurons mediate vasoconstriction and increased peripheral resistance." (PMID 34674633, 2021). "A total of 37 hypertensive patients under chronic renin–angiotensin system (RAS) suppression with ACR values in the normoalbuminuria range were included and classified as control (C) (ACR < 10 mg/g) and high-normal (HN) (ACR = 10–30 mg/g)." (PMID 34356333, 2021). "Intravenous injection of succinate into rats and mice induces hypertension via activation of the renin–angiotensin system, and this response is abolished in GPR91-deficient mice." (PMID 33574248, 2021). "AME is characterized by hypertension, hypokalemia, metabolic alkalosis, and low plasma renin activity, and aldosterone level." (PMID 34206115, 2021). "Cangiano JL, Rodriguez-Sargent C, Martinez-Maldonado M. Effects of antihypertensive treatment on systolic blood pressure and renin in experimental hypertension in rats." (PMID 33566958, 2021). "Obesity contributes to hypertension by several mechanisms, including sympathetic nervous system activation, increased free fatty acids, renin‐angiotensin system activation, and angiotensin II production in adipose tissue." (PMID 34418281, 2021). "At present, the research of Ang-III mainly concentrates on hypertension and the central renin-angiotensin system (RAS)." (PMID 34603502, 2021). "Polymorphisms in the ACE gene, encoding one of the components of the renin–angiotensin–aldosterone system (RAAS), have been found to be associated with a variety of cardiovascular diseases, such as hypertension, myocardial infarction, and cardiomyopathy." (PMID 34750628, 2021). "We investigated the role of the interaction between hypertension and the renin-angiotensin system in the pathophysiology of myocardial ischemia/reperfusion injury." (PMID 34122103, 2021).
Hypertension (continued). "Currently, angiotensin-converting enzyme (ACE) inhibitors are targeted as an alternative treatment of hypertension via the renin-angiotensin-aldosterone (RAAS) hormonal cascade." (PMID 33670795, 2021). "Previous studies have demonstrated that SS rats are considered a low renin model of hypertension and are resistant to ACE inhibitors." (PMID 34975523, 2021). "Two-kidney-one-clip (2K1C) as a model of renin-dependent hypertension and IR alter the balance between two axes of RAS." (PMID 33986960, 2021). "Patients with tumors carrying ARMC5 variants presented with varying levels of hyperaldosteronism, low-renin hypertension, and decreased expression of CYP11B2." (PMID 33800142, 2021). "Elevated sympathetic activity, inflammation, and, most of all, over-activity of the renin–angiotensin system are the main factors contributing to the development of hypertension." (PMID 35111064, 2021). "Together, these results support that S1P-derived sPRR mediates Ang II–induced hypertension through enhancement of intrarenal renin level and activation of ENaC." (PMID 33280408, 2021). "Renin production leads to an increase in mean arterial pressure, and thus it is expected that an induction of renin production would lead to hypertension." (PMID 34277961, 2021). "Under pathological conditions, the PVH drives inflammation through activation of NF-κB, thereby increasing the activity of the renin-angiotensin system, leading to hypertension." (PMID 34040073, 2021). "The angiotensin–renin system, in fact, is dysregulated in subjects with hypertension and SARS-CoV-2 infection." (PMID 34442038, 2021). "The renin-angiotensin system (RAS) has a prominent role in the pathogenesis of hypertension and related organ damage." (PMID 34440064, 2021). "Eventually, cause elevated leakage protein from the glomerulus, glomerular collapse, glomerulonecrosis, and necrosis Renin-angiotensin-aldosterone system (RAAS) in hypertension also sabotage renal function." (PMID 34886533, 2021). "It has been previously reported that activators or blockers of thrombin-activated PAR-1 evoke a decrease and increase in blood pressure in healthy animals, respectively, whereas the blockade of PAR-1 in renin-overexpressing mice reduces hypertension." (PMID 34445374, 2021). "Our results indicated that in patients with type 2 diabetes, urine renin activity increased as the concurrence of diabetes status, hypertension, eGFR < 60 mL/min per 1.73 m2, and/or ACR also increased (Supplemental)." (PMID 33933156, 2021). "Hypertension develops in a complex phenomenon of the sympathetic nervous system and the renin-angiotensin-aldosterone system." (PMID 33688497, 2021). "Systemic hypertension not only affects tissue remodeling or vascular wall inflammation by exerting abnormal hemodynamic stresses but also activates the local renin–angiotensin system." (PMID 34092261, 2021). "In another renal programming model induced by placental insufficiency in the Sprague Dawley rat, adult offspring developed hypertension in conjunction with increased renin and AGT mRNA, as well as increased ACE activity at 16 weeks of age." (PMID 33669059, 2021). "Combining the outcomes from both target lists, we selected ACE, AGT, AGTR1, and REN as important targets in COVID-19 for hypertension patients." (PMID 34067609, 2021). "Excess activation of the renin-angiotensin system plays an essential role in the pathogenesis of hypertension." (PMID 34650444, 2021). "In the 2K1C rat model hypertension is induced by temporarily restricting blood flow to one kidney, which activates the renin-angiotensin axis and induces hypertension." (PMID 33848877, 2021). "A high incidence of hypertension (75%) in our cohort study among hospitalized COVID-19 patients can be related to renin-angiotensin system (RAS) imbalance and endothelial dysfunction." (PMID 34604534, 2021).